CD47 (CD47 molecule)
Diseases named in the same sentence as CD47 in open-access papers (continued):
Sharing a sentence is not in itself a finding about the gene and the disease.
cervical cancer (continued). "Cervix cancer cases reported 59% cases gained CD36 copy number, 95% cases gained CD47 copy number, and 58% of cases lost TSP-1 copy number." (PMID 39627379, 2024). "The protein expression and positive ratio of LSD1 increased steadily, as did those of the CD47 and PD-L1 proteins, in the progression from normal cervical to CIN and then to cervical cancer." (PMID 33731702, 2021). "Accordingly, the protein expression level of CD24/CD47 in cervical cancer was significantly higher than that of normal cervical tissue." (PMID 41354057, 2025). "This suggested that CD47 and PD-L1 expression could be directly regulated through LSD1-mediated H3K4 demethylation in cervical cancer." (PMID 33731702, 2021). "To further confirm the correlation between LSD1 expression and CD47/PD-L1 expression, we performed 201 instances of immunohistochemistry staining in tissue microarrays, including normal cervical tissues, CIN tissues, and cervical cancer tissues." (PMID 33731702, 2021). "To date, there have been no molecular biological studies of CD47 expression in cervical carcinoma." (PMID 36611344, 2022).
neuroblastoma (22 papers, 2017 to 2025). Neuroblastoma (NB) is the most common solid, extracranial childhood tumor. "CD47 was widely expressed in various cell types (tumor cells and stroma cells) in high-risk neuroblastoma tissues." (PMID 38920727, 2024). "Below, we will describe the polarization status of macrophages versus their phagocytic capacity in high-risk neuroblastoma at diagnosis and the CD47-SIRPA axis in cancer immunotherapy." (PMID 38920727, 2024). "To determine the cell types expressing CD47 in high-risk neuroblastoma tissues, we performed immunohistochemical analysis on six high-risk neuroblastoma specimens." (PMID 38920727, 2024). "In this article, we discuss our perspective on the CD47/SIRPA blockade therapy in high-risk neuroblastoma and the dual role of the inhibitory receptor SIRPA on macrophages." (PMID 38920727, 2024). "In contrast to CD47 expression, among the six high-risk neuroblastoma tumors examined, SIRPA expression was mainly observed in macrophages." (PMID 38920727, 2024). "Consistent with this notion, it has been shown recently that the CD47/SIRPA blockade therapy with anti-CD47 antibody in xenograft models of high-risk neuroblastoma requires an additional opsonizing antibody against neuroblastoma, such as anti-GD2 antibody, to be efficacious." (PMID 38920727, 2024). "CD47 staining was also detected in the vasculature of high-risk neuroblastoma." (PMID 38920727, 2024). "Among high-risk neuroblastoma with MYCN amplification, weak cell membrane staining of CD47 was detected and high CD47 expression was detected on neurites of the tumor cells." (PMID 38920727, 2024). "For instance, the combination of anti-GD2 and anti-CD47 has been found to synergistically facilitate the eradication of neuroblastoma by altering both pro- and anti-phagocytic signals within the tumor microenvironment." (PMID 38532108, 2024). "CD47 promoted neurite formation in mouse neuroblastoma N1E-115 cells by activating the members of the Rho family of small G proteins Rac and Cdc42; here, the CD47 IgV domain was sufficient, and the MMS domain and short cytoplasmic tail were dispensable." (PMID 38426113, 2024). "The already described anti-GD2/CD47 combination, and a case report of two refractory neuroblastoma patients treated with anti-GD2/PD-1 combination therapy illustrate the potential of such combinations." (PMID 38181797, 2024). "CD47 is expressed on both tumor and stroma cells, whereas SIRPA expression is restricted to macrophages in high-risk neuroblastoma tissues." (PMID 38920727, 2024). "Dinutuximab induced neutrophil-mediated killing of unmodified neuroblastoma cell lines up to 5–20%, whereas up to 80% killing was achieved in CD47 knockout cell lines." (PMID 38087370, 2023). "CD47, known as the 'don't eat me' signal, is frequently upregulated in various cancers, including neuroblastoma." (PMID 38087370, 2023). "Encouraged by these findings, a clinical trial investigating the combination of anti-GD2 (dinutuximab) and anti-CD47 (magrolimab) antibodies in neuroblastoma relapse patients was initiated (NCT04751383)." (PMID 38087370, 2023). "In a variety of neuroblastoma cell lines, knocking down CD47 or blocking SIRPα on neutrophils increased the neutrophil-mediated ADCC induced by dinutuximab (anti-GD2 antibody)." (PMID 35865547, 2022). "Blocking the CD47-SIRPα interaction also increased ADCC capacity in primary patient-derived neuroblastoma spheroid cells as long as GD2 expression was sufficient, once again highlighting the relevance of combination therapy." (PMID 35865547, 2022). "We found that human neuroblastoma tumors expressed significantly higher levels of the immune checkpoint molecule CD47 relative to normal adrenal gland tissue, suggesting a pronounced ~twofold upregulation on mRNA level of the molecule." (PMID 34503071, 2021).
neuroblastoma (continued). "Overall, this provides a rational basis for the targeting of CD47-SIRPα interactions to improve the clinical response to anti-GD2 therapy in children suffering from neuroblastoma." (PMID 34503071, 2021). "First, we examined CD47 mRNA expression on a panel of 24 neuroblastoma cell lines from tissue banks which included cells of both phenotypes." (PMID 34503071, 2021). "We demonstrate here that the capacity of neutrophils to kill dinutuximab-opsonized neuroblastoma cells is controlled by the CD47-SIRPα axis and its disruption promotes their cytotoxic potential even further, significantly improving dinutuximab responsiveness." (PMID 34503071, 2021). "This was shown by either genetically deleting CD47 molecules from the surface of several neuroblastoma cells or by using a blocking antibody for SIRPα." (PMID 34503071, 2021). "To assess the relevance of CD47-SIRPα signaling in neuroblastoma, we first examined the gene expression levels of CD47 in this tumor type and compared it to the levels in the respective healthy tissue, being the adrenal gland in our case." (PMID 34503071, 2021). "Here, we demonstrate that the capacity of neutrophils to kill dinutuximab-opsonized neuroblastoma cells is also controlled by the CD47-SIRPα axis and can be further enhanced by antagonizing CD47-SIRPα interactions." (PMID 34503071, 2021). "In the present study, we have investigated the role of the CD47-SIRPα innate immune checkpoint in the context of antibody therapy with dinutuximab in neuroblastoma." (PMID 34503071, 2021). "First, we provided evidence of neutrophil infiltration in neuroblastoma tumors, as well as an upregulation of CD47 molecule throughout all disease stages relative to the levels found in the adrenal gland." (PMID 34503071, 2021). "To investigate the role of CD47-SIRPα as checkpoint in neutrophil-mediated ADCC in neuroblastoma, we verified CD47 expression in the GD2-positive neuroblastoma cell lines NMB, LAN-1, and IMR-32." (PMID 34503071, 2021). "For comparison, we examined CD47 expression in favorable histology neuroblastoma." (PMID 38920727, 2024). "To better evaluate the involvement of CD47-SIRPα axis in the two divergent phenotypes that can be found in neuroblastoma, we examined CD47 expression in four isogenic neuroblastoma cell line pairs with opposite phenotypes that were isolated from individual patients." (PMID 34503071, 2021). "In combination with CD47-SIRPα checkpoint blockade, this could be a feasible alternative to dinutuximab for patients with GD2-negative/low neuroblastoma variants." (PMID 34503071, 2021). "Therefore, we sought to investigate the involvement of CD47-SIRPα axis in neuroblastoma cells of mesenchymal phenotype as well." (PMID 34503071, 2021). "Of note, as for the genetically unmodified target cells, no killing of the CD47 deleted cells occurred in the absence of the therapeutic antibody dinutuximab, demonstrating that CD47–SIRPα interactions only control antibody-dependent mechanisms of neuroblastoma killing by neutrophils." (PMID 34503071, 2021). "By testing cells of either an adrenergic or mesenchymal phenotype, the two divergent cellular phenotypes responsible for a large part of the tumor heterogeneity found in neuroblastoma, we further characterized the involvement of CD47-SIRPα checkpoint in this cancer type." (PMID 34503071, 2021). "Neuroblastoma patient samples were shown to have ubiquitous expression of CD47 and mouse xenograft models have demonstrated significant response to the blockade of CD47 and TSP-1." (PMID 35582455, 2020). "In addition, among the six high-risk neuroblastoma tumors examined, we observed a difference in CD47 staining in high-risk neuroblastoma with MYCN amplification vs. those without MYCN amplification." (PMID 38920727, 2024).
neuroblastoma (continued). "Here, we examined whether an inhibition of CD47-SIRPα axis, by either a genetic disruption or by using an antagonistic agent for SIRPα, allows neutrophils to more efficiently kill dinutuximab-opsonized neuroblastoma cells in vitro." (PMID 34503071, 2021). "Importantly, the most compelling enhancing effect was seen for unstimulated neutrophils, for which unmodified neuroblastoma cells as targets barely resulted in 5–20% of killing, whereas for the CD47 KO cell lines, the neutrophil-mediated cytotoxicity levels were enhanced up to 50–80%." (PMID 34503071, 2021). "Consequently, not only enhanced CD47 expression on the tumor, but also decreased expression of TAAs on tumor cells can reduce or preclude neutrophil-mediated killing, as observed, e.g., in neuroblastoma cells of the mesenchymal phenotype that have lost GD2 expression." (PMID 35884427, 2022). "Given that neutrophil ADCC is a dominant effector mechanism leading to the eradication of dinutuximab-opsonized neuroblastoma cells, we have investigated the therapeutic potential of anti-GD2 antibody in combination with CD47-SIRPα inhibition." (PMID 34503071, 2021). "Observations made in human neuroblastoma cells and mouse primary cortical neurons show that transcription factor α-Pal/NRF-1 acting through CD47/IAP promoted neurite outgrowth and reduced expression of α-Pal/NRF-1 acting through CD47/IAP impaired neurite outgrowth." (PMID 37872624, 2023). "Similarly, anti-CD47 mAbs enhance neutrophil-mediated ADCC of solid cancers in vitro, such as neuroblastoma." (PMID 35884427, 2022). "In particular, CD47-SIRPa checkpoint inhibition enhanced neutrophil-mediated ADCC of dinutuximab-opsonized adrenergic neuroblastoma cells, whereas mesenchymal neuroblastoma cells may evade immune recognition by a reduction of GD2 expression." (PMID 34503071, 2021). "In line with our data on CD47 KO neuroblastoma cells, we found the SIRPα blocking agent alone did not induce neutrophil-mediated cytotoxicity of tumor cells unopsonized with dinituximab." (PMID 34503071, 2021). "The involvement of the CD47-SIRPα checkpoint in neuroblastoma has, however, not been thoroughly investigated yet." (PMID 34503071, 2021). "Therefore, MYC but not MYCN or CD47 expression in neuroblastoma cells appears to be a significant regulator of T cell function in the tumor microenvironment." (PMID 36768931, 2023). "In addition, we hypothesize that an effective and less toxic cure for high-risk neuroblastoma should target SIRPA on macrophages and not CD47 on the tumor cells." (PMID 38920727, 2024).
brain tumors (20 papers, 2016 to 2025). "Emerging immunotherapeutic and targeted approaches, including CAR-T cell therapy, PD-1 pathway blockade, CD47-targeted nanotherapeutics, engineered probiotics, and ferroptosis-inducing cancer vaccines, demonstrate substantial promise in brain tumor treatment." (PMID 40948940, 2025). "CD47 Y288F knock‐in expression reduced CD47 expression, increased macrophage phagocytosis of tumor cells, and inhibited brain tumor growth in mice." (PMID 37541303, 2023). "Knock‐in expression of CD47 Y288F reduces CD47 expression, increases macrophage phagocytosis of tumor cells, and inhibits brain tumor growth in mice." (PMID 37541303, 2023). "Although the CD47- SIRPα axis blockade revealed beneficial effects in the struggle against brain tumors, additional pro-phagocytic stimuli are required for complete eradication of the tumor." (PMID 35054787, 2022). "Here, we demonstrated the ability of our assay to evaluate the effect of blocking one of the "don't eat me" signals, CD47, on phagocytosis of human brain tumors." (PMID 33209523, 2020). "Human brain tumor cells will be treated with anti-CD47 antibodies or different doses of irradiation prior to adding monocyte-derived macrophages." (PMID 33209523, 2020). "As an example of immunotherapy treatment, we used a monoclonal antibody to block an anti-phagocytic signal (CD47) to evaluate the assay using human brain tumor cells and monocyte-derived macrophages." (PMID 33209523, 2020). "We recently showed that disruption of the SIRPα-CD47 signaling axis is efficacious against various brain tumors including GBM primarily by inducing tumor phagocytosis." (PMID 30602457, 2019). "CD47 is ubiquitously overexpressed on malignant human tumors, including malignant pediatric brain tumors and GBM." (PMID 30602457, 2019). "ZDHHC17, known for its role in neuronal protein trafficking, might similarly influence CD47 localization in neuroinflammatory or brain tumour microenvironments." (PMID 41163221, 2025). "Furthermore, the results successfully demonstrate that anti-CD47 antibodies and irradiation can enhance the macrophage-mediated phagocytosis of brain tumors." (PMID 33209523, 2020). "While we have previously shown that blocking the myeloid checkpoint CD47-SIRPα axis is efficacious against multiple adult and pediatric brain tumors, the specific role of microglia in anti-CD47 treatment remains unclear." (PMID 30602457, 2019). "CD47 is overexpressed by malignant cells to evade the innate immune response and may be particularly enriched in pediatric brain tumors including medulloblastoma, acute teratoid rhabdoid tumor, pediatric glioblastoma, and DIPG." (PMID 29065490, 2017). "come to a similar conclusion that humanized CD47 antibody HU5F9-G4 inhibits CD47 expression, enhanced tumor cell phagocytosis by macrophage, improves the survival time of animals, and has nontoxic effects on neurons and other tissues in a xenograft model derived from the malignant brain tumor." (PMID 33329583, 2020). "By antagonizing CD47 (which binds to activating signal regulatory protein-alpha (SIRPalpha) on myeloid cells) with a humanized mAb, pre-clinical investigations have demonstrated that macrophages can be unlocked to phagocytize tumor cells in several pediatric brain tumor models." (PMID 29065490, 2017). "Therefore, for brain tumors, blockade of the CD47-SIRPα pathway may generate promising effects." (PMID 32944390, 2020). "Future studies are needed to explore whether CD24, CD47, or CD276 (B7H3) inhibitors would constitute alternative immunotherapy approaches in CMMRD‐derived brain tumors." (PMID 40880425, 2025).
prostate carcinoma (20 papers, 2015 to 2026). A carcinoma that arises from epithelial cells of the prostate gland. "Disruption of CD47 in PC3 prostate cancer cells similarly decreased schlafen-11 expression and was associated with a CD47-dependent decrease in acetylation and increased methylation of histone H3 in the SLFN11 promoter region." (PMID 31632920, 2019). "Here we investigated the role of CD47 expression in tumor stroma in tumorigenesis by comparing tumor growth in wild-type (WT) and CD47-deficient mice after subcutaneous injection of syngeneic prostate cancer cells." (PMID 27283989, 2017). "CD47 was associated with prostate cancer invasion, angiogenesis, resting, and proliferation." (PMID 37719086, 2023). "According to these findings, immune cell infiltration in prostate carcinoma may be linked to CD47." (PMID 37719086, 2023). "CD4+T cell infiltration take part in the development and spread of prostate cancer, and neutrophils are linked to poor prognosis.Therefore, we proposed that the expression level of CD47 might affect TME through immune cell infiltration, thus regulating tumor progression." (PMID 37719086, 2023). "Future work will be extended to in vivo studies to evaluate tumor accumulation and therapeutic efficacy, such as using CD47-humanized mouse models bearing stably CD47-transfected RM-1 prostate cancer tumors (FRα+/PD-L1+)." (PMID 41226252, 2025). "Understanding the mechanisms that regulate CD36 + M2 TAM infiltration and high CD47 expression in tumour cells within the prostate cancer tumour microenvironment (TME) is essential." (PMID 41163221, 2025). "Here we report that the reverse signaling using CD47 as a receptor additionally enhances a pro-survival function of prostate cancer cells under phagocytic attack." (PMID 37848444, 2023). "Our research demonstrates a closely relationship among CD47 and the immunological microenvironment of prostate cancer, and blocking CD47 can promote macrophages to phagocytosis of prostate cancer cells." (PMID 37719086, 2023). "In summary, our findings suggest that the level of immune infiltration of prostate cancer is connected with the expression level of CD47, and blocking CD47 in vitro can promote macrophages to phagocytosis of prostate cancer cells." (PMID 37719086, 2023). "The immune infiltration degree of prostate cancer was explored utilizing the TIMER database for further investigate the connection among CD47 and the immunological microenvironment of prostate cancer." (PMID 37719086, 2023). "Here the authors show that low CD47-expressing prostate cancer cells still allow phagocytosis but the process is incomplete leading to the formation of macrophage:tumor hybrid cells with immune evasive and pro-metastatic properties." (PMID 37848444, 2023). "The objective of this study is to look into the connection among CD47 and immune cell infiltration in prostate tumor, with the goal of providing a fresh strategy for treating prostate cancer." (PMID 37719086, 2023). "Using the TIMER database to investigate the infiltration of immune-related cells within prostate carcinoma, it was discovered that M2-like TAMs and Treg cell invasion proportions also increased in the prostate cancer microenvironment with high-CD47 expression." (PMID 37719086, 2023). "Motivated by the need to investigate the function of CD47-SIRPα reverse signaling, we conduct phagocytosis assays in prostate cancer cells expressing different levels of CD47." (PMID 37848444, 2023). "By using TIMER, the connection among CD47 and immunological invasion of prostate cancer was explored." (PMID 37719086, 2023). "To further verify the impact of CD47 as a potential target on prostate cancer TME, we used aCD47 antibody to block RM-1 and observe the phagocytosis efficiency of M1-like macrophages on it." (PMID 37719086, 2023). "Expression level of CD47 is upregulated in prostate carcinoma, and it is closely connected with prostate cancer's inadequate immune invasion." (PMID 37719086, 2023).